ETV4 (ETS variant transcription factor 4)
Diseases named in the same sentence as ETV4 in open-access papers (continued):
Sharing a sentence is not in itself a finding about the gene and the disease.
bladder cancer (6 papers, 2016 to 2025). "PTK6 induced phosphorylation of ETV4 and increased nuclear translocation of ETV4, leading to enhanced metastasis in bladder cancer." (PMID 40777122, 2025). "Therefore, ETV4 is a therapeutic target of TANs-mediated lymphangiogenesis and lymphatic metastasis of bladder cancer." (PMID 39726782, 2024). "Mechanistically, transcription factor ETV4 enhances bladder cancer cells-derived CXCL1/8 to recruit TANs, increasing VEGFA and MMP9 secretion from TANs to promote lymphangiogenesis and lymphatic metastasis of bladder cancer." (PMID 39726782, 2024).
breast tumor (6 papers, 2006 to 2021). "ETV4 is overexpressed in breast tumors and is associated with distant metastasis and poor prognosis." (PMID 29996935, 2018). "Indeed, ETV4 is overexpressed in breast tumors and is associated with distant metastasis and poor prognosis." (PMID 29996935, 2018). "c Metastasis-free survival (MFS) curves for patients with breast tumors according to Low-ETV4 (n = 13) and High-ETV4 (n = 251) mRNA levels." (PMID 29996935, 2018). "b Metastasis-free survival (MFS) curves for patients with breast tumors according to Low-ETV4 (n = 82) and High-ETV4 (n = 374) mRNA levels." (PMID 29996935, 2018). "a Metastasis-free survival (MFS) curves for patients with breast tumors according to Low-ETV4 (n = 12), High-ETV4 and Low-MMP13 (n = 243), or High-ETV4 and High-MMP13 (n = 9) mRNA levels." (PMID 29996935, 2018). "Although overexpression of PEA3 (E1AF/ETV4), and of the related factors ERM (ETV5) and ER81 (ETV1), have been observed in human and mouse breast tumors, PEA3 factors have also been ascribed a tumor suppressor function." (PMID 20107508, 2010).
gastric adenocarcinoma (6 papers, 2010 to 2023). "As a member of oncogenic ETS genes, ETV4 protien has been reported to promote cancer metastasis in mouse models and is associated with poor prognosis in gastric adenocarcinoma." (PMID 25860484, 2015). "In the same way, in gastric adenocarcinoma cell lines, ETV4 increases MMP1 and MMP7 expression and stimulates invasion in vitro." (PMID 29996935, 2018). "The three tumors most strongly correlated with ETV4 expression were PRAD, COAD, stomach adenocarcinoma (STAD) (StromalScore); PRAD,COAD, STAD (ImmuneScore); and PRAD, COAD, STAD (ESTIMATEScore)." (PMID 37205199, 2023).
gastrointestinal stromal tumor (6 papers, 2014 to 2020). "Knockdown of ETV4 suppressed tumor cell proliferation, growth, and aggressiveness of gastrointestinal stromal tumor." (PMID 30460327, 2018). "ETV4 modulates cell cycle regulation and Wnt/β-catenin signaling, which is important in potentiating gastrointestinal stromal tumor malignancy." (PMID 30460327, 2018). "The oncogene c-Kit drives IDO expression in gastrointestinal stromal tumors (GIST) via the mammalian target of rapamycin (mTOR) and the transcription factor ETV4." (PMID 24657910, 2014). "Consistent with this, ETV4 stabilizes β-catenin, a key transcription factor mediating WNT signaling, to promote tumor aggressiveness in gastrointestinal stromal tumors." (PMID 32042269, 2020).
lymph node metastasis (5 papers, 2020 to 2024). "In patients with lymph node metastasis of CRC, ETV4 expression was significantly upregulated, whereas SPDEF and SPIB expression was significantly downregulated." (PMID 38200280, 2024). "Expression of miR-29b and ETV4 was measured in CRC patients with or without lymph node metastasis (LNM), with different differentiation grade and TNM stages." (PMID 33407520, 2021).
thyroid cancer (5 papers, 2020 to 2025). "Research shows that ETV4 is associated with tumor progression in several cancer types; in thyroid cancer, it may bind to the mutated TERT promoter, therefore increasing TERT expression." (PMID 32982961, 2020). "In particular, ETV4 was one of the transcript targets, previously reported to participate in the regulation proliferation and metastasis of thyroid cancer." (PMID 34409028, 2021).
triple-negative breast carcinoma (5 papers, 2011 to 2020). An invasive breast carcinoma which is negative for expression of estrogen receptor (ER), progesterone receptor (PR), and human epidermal growth factor receptor 2 (HER2). "Further, ERK activation in turn stimulates the expression of the transcription factor, ETV4/PEA3; a gene expression pattern associated with a higher risk of distant metastasis in basal/triple-negative breast cancers." (PMID 32340151, 2020). "ETV4 overexpression is associated with increased metastatic risk and poor patient survival in triple-negative breast cancer distant metastasis and poor patient survival." (PMID 29996935, 2018). "One of them was the transcription factor ETV4/PEA3, which has been associated with metastasis in different tumor types, including breast adenocarcinomas in general and triple-negative breast cancers in particular." (PMID 27340777, 2016). "It has been described that ETV4 expression is controlled by ERK in esophageal cancer and so we found in our triple-negative breast cancer setting." (PMID 27340777, 2016).
colon adenocarcinoma (4 papers, 2021 to 2024). "Moreover, ETV4 is one of the most expressed genes in colon adenocarcinoma, and it is related to cell proliferation, colony formation, and cell migration." (PMID 39228892, 2024). "ETV4 or ETS Variant Transcription factor 4 (E1A enhancer-binding protein – E1AF or Polyoma Enhancer Activator 3 Homologue) is a known transcription factor, upregulated and activated in colon adenocarcinoma." (PMID 34824625, 2021). "Furthermore, we found a significantly higher expression of ETV4 and ETV5 in cancer tissues of both colon adenocarcinoma (COAD) and rectal adenocarcinoma (READ) via TIMER." (PMID 35860243, 2022). "In comparison with normal tissues, ETV4 expression was remarkably elevated in 17 tumors such as glioblastoma multiforme (GBM), lung adenocarcinoma (LUAD), colon adenocarcinoma (COAD), esophageal carcinoma, and colon adenocarcinoma/rectum adenocarcinoma esophageal carcinoma (COADREAD)." (PMID 37205199, 2023).
glioblastoma (4 papers, 2023 to 2025). The most malignant astrocytic tumor (WHO grade IV). "The selected GSC superenhancers were enriched for transcriptional motifs, including NR4A2, SMAD3, and ETV4, which have been previously reported to promote glioblastoma malignancy." (PMID 36394953, 2023). "Among which, CDC73, PSMC2, SOCS3, and ETV4 were substantially upregulated; whereas PLK2 and LMO7 were substantially downregulated in glioblastoma cells than that in control." (PMID 41318472, 2025).
lung adenocarcinoma (4 papers, 2020 to 2025). A carcinoma that arises from the lung and is characterized by the presence of malignant glandular epithelial cells. "ETV4 promotes proliferation and invasion of lung adenocarcinoma by transcriptionally upregulating MSI2." (PMID 31992202, 2020). "At the mRNA level, TCGA data indicated that ETV4, MCM2/4/5/10, and ORC1 mRNA levels were all significantly upregulated in 515 lung adenocarcinoma (LUAD) and 503 lung squamous cell carcinoma (LUSC) compared with normal lung tissue." (PMID 40548893, 2025).
metastatic disease (4 papers, 2010 to 2024). "We freshly isolated bulk tumor cells from four patients with metastatic disease and high ETV4 expression, and injected the cells into the flanks of NSG mice." (PMID 29371979, 2017). "In addition, we also noticed that ETV4 expression significantly increased in the metastatic tumor comparing to the primary tumor from TCGA data, and the expression level of ETV4 in metastatic cancer cells is higher than that in primary cancer cells from scRNA-seq data." (PMID 38849954, 2024).
prostate adenocarcinoma (4 papers, 2022 to 2025). "Interestingly, we observed a decrease in ETV4 expression in prostate adenocarcinoma (PRAD)." (PMID 40469297, 2025). "In some tumors, ETV4 expression was lower than in normal tissues: kidney renal papillary cell carcinoma (KIRP), prostate adenocarcinoma (PRAD), pan-kidney cohort (KIPAN), kidney renal clear cell carcinoma (KIRC), and pheochromocytoma and paraganglioma (PCPG)." (PMID 37205199, 2023). "The consortium published the status of ERG, ETV1, ETV4, and FLI1 fusions in the cBioportal database (dataset: Prostate Adenocarcinoma (TCGA, Cell 2015)) for 333 samples." (PMID 37349736, 2023).
adenoma (3 papers, 2005 to 2021). A neoplasm arising from the epithelium. "Among the differentially expressed genes (DEG), the ETV4 gene, a variant transcription factor of the ETS family, showed high upregulated expression in the adenocarcinoma samples as compared to adenoma." (PMID 33648461, 2021).
cervical cancer (3 papers, 2009 to 2026). A primary or metastatic malignant neoplasm involving the cervix. "In the 1990s, ETV4 was regarded as a tumor suppressor gene because it was able to increase luciferase expression driven by the CDKN1A promoter in SiHA cervical cancer cells whereas its deletion reduced CDKN1A levels in Saos2 osteosarcoma cells." (PMID 32791988, 2020).
diabetes (3 papers, 2012 to 2022). "Notably, the relationships of ETS translocation variant 4 (Etv4) and transcription factor AP-2 beta (Tcfap2b) to adipogenesis, which is strongly related to diabetes, have been reported, together with their association with the other pathways." (PMID 23046543, 2012).
endometrial cancer (3 papers, 2022 to 2023). Primary or metastatic malignant neoplasm involving the endometrium (mucous membrane that lines the endometrial cavity). "Likewise, it has been shown that deletion of the ETS translocation variant 4 (ETV4), a candidate factor controlling ER genomic binding in endometrial cancer cells, led to decreased growth in 3D cultures of the Ishikawa endometrial cancer cell line." (PMID 35692756, 2022).
esophageal squamous cell carcinoma (3 papers, 2023 to 2025). Esophageal squamous cell carcinoma (ESCC) is a type of esophageal carcinoma (EC) that can affect any part of the esophagus, but is usually located in the upper or middle third. "ETV4, as part of the MAPK pathway, has also been shown to promote the occurrence and metastasis of esophageal squamous cell carcinoma." (PMID 40469297, 2025). "ETV4 transcription factor expression inhibits the expression of ubiquitin ligase RNF2, leading to increased expression of the key enzyme CPT1A involved in fatty acid oxidation, thereby playing a role in esophageal squamous cell carcinoma." (PMID 39944823, 2025).
Obesity (3 papers, 2020 to 2025). Accumulation of substantial excess body fat. "Using gain- and loss-of-function approaches, we reveal that ETV4 enhances uncoupled respiration and thermogenesis, thereby protecting mice from diet-induced obesity and insulin resistance." (PMID 40324882, 2025). "In conclusion, Etv4 promotes thermogenesis and enhances systemic metabolism by upregulating Ucp1 expression, thereby providing protection against diet-induced obesity and insulin resistance." (PMID 40324882, 2025). "The −12 kb enhancer and ETV4 can be potential therapeutic targets for combating obesity and improving metabolic health." (PMID 40324882, 2025). "We further identified the transcription factor ETV4 as a key regulator that binds this enhancer, modulates chromatin accessibility, and drives UCP1 expression, thereby promoting thermogenesis and metabolic protection against obesity and diabetes." (PMID 40324882, 2025).
oesophageal adenocarcinoma (3 papers, 2010 to 2023). "Indeed, members of the PEA3 subfamily, ETV1, ETV4 and ETV5 have been implicated in a wide range of cancers [reviewed in 15] and ETV4 has been implicated in oesophageal adenocarcinomas." (PMID 28859074, 2017). "Here, we have studied the expression of the PEA3 subfamily members PEA3/ETV4 and ER81/ETV1 in oesophageal adenocarcinomas and determined their role in oesophageal adenocarcinoma cell function." (PMID 21143918, 2010).
oesophageal cancer (3 papers, 2010 to 2023). "Association analysis of disease-free-interval showed that ETV4 expression was a hazard factor in lung squamous cell carcinoma, COADREAD, COAD, and PCPG, but was a favorable factor in esophageal carcinoma." (PMID 37205199, 2023). "ETV4 was positively associated with MSI in CESC, KIPAN, MESO, skin cutaneous melanoma and kidney chromophobe and negatively associated with MSI in COAD, COADREAD, stomach and esophageal carcinoma, STAD and GBMLGG." (PMID 37205199, 2023).
prostatic intraepithelial neoplasia (3 papers, 2020 to 2023). "Lower-level expression of ETV4 caused mild luminal cell expansion without histologic abnormalities, and higher-level expression of stabilized ETV4 caused prostatic intraepithelial neoplasia (mPIN) with 100% penetrance within 1 week." (PMID 37018402, 2023). "Here, we report a novel transgenic mouse model in which the overexpression of human ETV4 in the prostate results in late development of mouse prostatic intraepithelial neoplasia (mPIN)." (PMID 32791988, 2020). "ETV4 mice, from two independent transgenic lines, have increased cell proliferation in their prostate and two-thirds of them, by the age of 10 months, developed mouse prostatic intraepithelial neoplasia (mPIN)." (PMID 32791988, 2020).
rectal adenocarcinoma (3 papers, 2022 to 2025). "In rectal adenocarcinoma, an ETV4/Hes1/STAT3 signaling axis has been identified: the transcription factor ETV4 activates Hes1 transcription by binding to its promoter, which subsequently drives STAT3 phosphorylation to promote tumor proliferation and metastasis." (PMID 40755759, 2025).
asthma (2 papers, 2019 to 2021). "ETS variant transcription factor 4 (ETV4) is a recently identified transcription factor that regulates gene expression-based biomarkers of asthma and IL6 production in an airway epithelial cell line." (PMID 34552174, 2021). "There was a cluster of six SNPs significantly associated with asthma between the ETV4 and MEOX1 genes." (PMID 34552174, 2021). "Both SNPs were expression quantitative trait loci, and the asthma risk alleles at both SNPs were correlated with increased levels of ETV4 mRNA expression." (PMID 34552174, 2021). "Given that ETV4 has not yet been implicated in asthma genetics, we performed genetic association studies of adult asthma in the ETV4 region using two independent Japanese cohorts (a total of 1532 controls and 783 cases)." (PMID 34552174, 2021). "The C alleles of rs4792901 and rs2880540, both of which are asthma risk alleles, were significantly associated with higher levels of ETV4 mRNA in lungs (P = 1.2E−4) and adipose tissue (P = 6.2E−7), respectively." (PMID 34552174, 2021). "Application of NeTFactor to a multi-gene expression-based asthma biomarker identified ETS translocation variant 4 (ETV4) and peroxisome proliferator-activated receptor gamma (PPARG) as the biomarker’s most significant TF regulators." (PMID 31506535, 2019). "Distinct from PPARG, far less is known about ETV4 (ETS variant 4) in the context of asthma." (PMID 31506535, 2019). "In conclusion, we have demonstrated that two eQTLs in the ETV4/MEOX1 region, rs4792901 and rs2880540, showed a significant association with the development of adult asthma in Japanese." (PMID 34552174, 2021). "Our findings imply that ETV4 is involved in the pathogenesis of asthma, possibly through the heightened production of IL6." (PMID 34552174, 2021). "These two SNPs were correlated with mRNA expression levels of ETV4 and Mesenchyme Homeobox 1 (MEOX1); asthma risk alleles at the two SNPs showed increased levels of mRNA expression of these genes." (PMID 34552174, 2021). "SNPs located between ETV4 and mesenchyme homeobox 1 (MEOX1) were significantly associated with adult asthma, including rs4792901 and rs2880540 (P = 5.63E−5 and 2.77E−5, respectively)." (PMID 34552174, 2021). "Application of NeTFactor to a cohort of asthmatics and controls indicated that PPARG and ETV4 were the most likely regulators of an asthma biomarker." (PMID 31506535, 2019). "Just these two TFs regulated 24 (27%) of the asthma biomarker genes, including SERPINE237 and CDHR338, asthma-associated genes co-regulated by ETV4 and PPARG." (PMID 31506535, 2019). "As ETV4 has not been reported in any genetic studies of asthma to date, we performed a candidate gene association study of the ETV4 gene with asthma in Japanese patients with adult asthma." (PMID 34552174, 2021). "In addition, siRNA-based knock-down of ETV4 in an airway epithelial cell line model has demonstrated a significant reduction of cytokine expression relevant to asthma, including IL6 and IL8." (PMID 34552174, 2021). "Although ETV4 has not been detected in any genetic studies of asthma to date, in the present study, we successfully identified eQTLs for ETV4/MEOX1 genes at 17q21.31 as significantly associated with adult asthma." (PMID 34552174, 2021). "While PPARG has been associated with airway inflammation, ETV4 has not yet been implicated in asthma, thus indicating the possibility of novel, disease-relevant discovery by NeTFactor." (PMID 31506535, 2019). "Given that rs2880540, an eQTL for MEOX1 as well as for ETV4, was associated with asthma independent of rs4792901, and the haplotype consisting of the two SNPs showed the strongest association with asthma, the combined effect of both genes may explain the findings in the current study." (PMID 34552174, 2021). "In addition to ETV4, MEOX1 (located in the vicinity of ETV4) is also a candidate molecule for the development of asthma via the Th17 pathway." (PMID 34552174, 2021).
Barrett's metaplasia (2 papers, 2010 to 2017). "It is therefore interesting to note that we previously showed co-upregulation of ERK signalling and ETV4 expression in OAC and that genes encoding members of the RAS/ERK signalling cascade such as EGFR and KRAS are often amplified in the transition from Barrett’s oesophagus to adenocarcinoma." (PMID 28859074, 2017).
clear cell renal cell carcinoma (2 papers, 2021 to 2025). "According to a recent study, ETV4 promotes the migration and metastasis of clear-cell renal-cell carcinoma in vitro and in vivo." (PMID 33997099, 2021). "Additionally, ETV4 binds to the FOSL1 promoter, relying on PI3K-AKT signaling to directly upregulate FOSL1, leading to metastasis and disease progression in clear cell renal cell carcinoma." (PMID 40469297, 2025).
colorectal tumor (2 papers, 2021 to 2025). "We also evaluated the effect of ETV4 gene knockdown on the migratory capacity of colorectal tumor cell lines." (PMID 33648461, 2021). "Together, these data suggested that ETV4 could accelerate colorectal tumor growth and metastasis in vivo." (PMID 41281746, 2025).
embryonal carcinoma (2 papers, 2013 to 2021). A non-seminomatous malignant germ cell tumor characterized by the presence of large germ cells with abundant cytoplasm resembling epithelial cells, geographic necrosis, high mitotic activity, and pseudoglandular and pseudopapillary structures formation. "Another Ets protein, Pea3/ETV4, was shown to regulate Nanog and Oct4 expression in pluripotent NCCIT embryonic carcinoma cells." (PMID 33672811, 2021).
pancreatic ductal adenocarcinoma (2 papers, 2024 to 2025). An infiltrating adenocarcinoma that arises from the epithelial cells of the pancreas. "In pancreatic ductal adenocarcinoma (PDAC), ETV4 overexpression promoted cell growth and facilitated cell cycle progression through transcriptional regulation of cyclin D1." (PMID 38849954, 2024). "For example, in pancreatic ductal adenocarcinoma (PDAC), ETV4 was demonstrated to be remarkably upregulated in tumor tissues compared with the normal tissues and could promote the cell growth by transcriptionally regulating Cyclin D139." (PMID 41281746, 2025).
Papillary Thyroid Carcinoma (2 papers, 2020 to 2023). "CRLF1 interacts with MYH9 to promote cell proliferation and metastasis via the ERK/ETV4 axis in papillary thyroid carcinoma." (PMID 37875476, 2023).